GBF1 (golgi brefeldin A resistant guanine nucleotide exchange factor 1)
Diseases named in the same sentence as GBF1 in open-access papers (continued):
Sharing a sentence is not in itself a finding about the gene and the disease.
infection (continued). "GBF1 inhibited cells were more sensitive to Triton extraction (data not shown), similar to what has been reported following disruption of the actin and vimentin cage during infection, suggesting that the cytoskeletal cage is compromised upon GBF1 inhibition." (PMID 21909260, 2011). "In this paper we show that in the context of normal virus replication, functional GBF1 is required for successful virus propagation, and GBF1-3A interactions determine the outcome of infection in the presence of BFA." (PMID 19023417, 2008). "Interaction between GBF1 and viral protein 3A determined the outcome of infection in the presence of BFA." (PMID 19023417, 2008). "Similarly, the ARF GTPase-activating protein GBF1 was suppressed across all cell lines following infection." (PMID 41157297, 2025). "However, both the relative infection rate and PV size significantly decreased at 48 hpi with Arf4 and GBF1 depletion." (PMID 38349168, 2024). "We next studied the localization of Arf1, Arf4, and GBF1 during P. berghei liver stage infection." (PMID 38349168, 2024). "The multidomain structure of GBF1 allows this protein to engage in numerous interactions with other proteins, leading GBF1 to participate in many different cellular processes and even in the process of infection of some bacteria." (PMID 32599855, 2020). "It will be important to determine whether the alterations in the actin and vimentin cytoskeleton during infection are directly or indirectly modulated by GBF1." (PMID 21909260, 2011). "Moreover, the Drosophila GBF1 ortholog garz has been identified as a candidate in genomic screens which tested the entry and infection of the pathogens Listeria monocytogenes and Candida albicans." (PMID 19707569, 2009). "To further explore the role of GBF1 during infection, we employed the well-characterized chemical inhibitor golgicide A (GCA) to selectively decrease GBF1-mediated Arf1 activation." (PMID 38349168, 2024). "Second, our GBF1 construct had a BFA-resistant Sec7 domain, which allowed us to perform infections in the presence of BFA." (PMID 36306280, 2022). "There was no detectable decrease in the full-length ALIX, ACLY, hnRNP K, RIPK1, GBF1, and PFAS proteins, suggesting that only a subset of these target proteins are cleaved during infection." (PMID 29437971, 2018). "At 24 h post-infection, depletion of GBF1 exerted partial inhibition viral RNA replication, although siRNA specific to ARF1 or GBF1 was functionally active." (PMID 28303920, 2017). "We found gene depletion of Arf4 and GBF1 had no impact on the relative infection rate at 4 hpi, indicating that parasite invasion was not hindered." (PMID 38349168, 2024). "Altogether, these results suggest that the role of GBF1 is not restricted to maintain a single type of transport but rather to coordinate different transport pathways that promote the infection of HCV." (PMID 32599855, 2020). "Infection in the presence of the solvents dimethyl sulfoxide (DMSO) and methanol (MeOH), as well as the known inhibitors of MHV RNA synthesis Brefeldin A (BrefA, inhibitor of GBF1) and MG132 (proteasome inhibitor, probably also affects MHV entry;) were included as controls." (PMID 25375324, 2014). "It would be interesting to determine whether GBF1 mutants that do not localize to the Golgi could rescue an infection inhibited by BFA or by GBF1 depletion." (PMID 24058576, 2013). "Thus, while GBF1 might play a role during infection, its function appears to be independent of Arf1." (PMID 38349168, 2024). "However, recent studies suggest that the role of GBF1 in infection could not be fully explained by GBF1 functioning solely in the assembly of COPI carriers." (PMID 30326556, 2018). "The other GBF1-dependent RNA viruses, which do not establish chronic infections unlike HCV, do not share this special requirement for GBF1 early during infection." (PMID 24058576, 2013).
infection (continued). "However, GBF1 does not colocalize with ORF1 protein, and its subcellular distribution is unmodified upon infection or overexpression of viral proteins, indicating that GBF1 is likely not recruited to replication sites." (PMID 34578211, 2021). "The elution peaks of GBF1 and ARF1 has not changed after EV71 infection compared to mock infection." (PMID 28303920, 2017).
cancer (4 papers, 2018 to 2026). A tumor composed of atypical neoplastic, often pleomorphic cells that invade other tissues. "The Arf1 small G protein and its activator GBF1 regulate Golgi-ER retrograde trafficking during mitosis and in cancer cells, at least in part through phosphorylation of GBF1 by mitotic kinases." (PMID 29632863, 2018). "This proves GBF1 as a one‐key regulator of protein secretion triggered by mechanical cues, and represents a novel target for antifibrotic treatment in conditions such as cancer and fibrosis." (PMID 41088785, 2026). "This stiffness‐dependent mechanism shapes the secretome and, when dysregulated, may drive diseases like cancer and fibrosis, highlighting GBF1 as a potential therapeutic target." (PMID 41088785, 2026). "To determine whether chemotherapy renders cancer cells sensitive to GBF1 inhibitors, we induced senescence by treatment with etoposide and subsequently treated them with GCA or BFA." (PMID 38012402, 2023).
tumor (3 papers, 2021 to 2022). "Our results showed that AML and CML differ in the expression of GBF1, CD177, OLFM4 and peptidylprolyl isomerase B (PPIB) implicated in the intercellular interactions and chemotaxis regulation to regulate tumor cell migration and invasion." (PMID 36230605, 2022). "After GBF1 knockdown, the expression of FAM129A was upregulated, but the MMP9 protein level was decreased, as well as the secretion thereof to the extracellular, which was different from that in tumor cells." (PMID 34513838, 2021).
neurodegenerative disease (1 paper, 2020). A disorder of the central nervous system characterized by gradual and progressive loss of neural tissue and neurologic function. "We also verify the remarkable conservation of functions betweengarz and its mammalian orthologue, GBF1, validating the use ofDrosophila as an alternative 3Rs-beneficial model to knock-out mice for studying the biology of GBF1, potentially involved in human neurodegenerative diseases." (PMID 32595956, 2020).
neurological disorders (1 paper, 2016). "Five known PKA substrates (FLNA, ACTB, SOX9, MAP4K1 and GBF1) interacted with the domain modules of NBEA and three of these are linked with neurological disorders (FLNA, ACTB, SOX9)." (PMID 26999814, 2016).
GBF1 also shares sentences with these, for which no sentence is quoted: Parkinson disease (2 papers); cardiac hypertrophy (1); cataract (1); Chlamydia infection (1); colon cancer (1); lung fibrosis (1); Parkinsonism (1); peripheral axonal neuropathy (1); peripheral neuropathies (1); Rotavirus infection (1); small cell lung carcinoma (1); type 2 diabetes (1); vasculopathy (1).